TF (transferrin)
Diseases named in the same sentence as TF in open-access papers (continued):
Sharing a sentence is not in itself a finding about the gene and the disease.
iron deficiency (continued). "A ferritin level lower than 100 μg/L or lower than 100–300 μg/L together with a transferrin saturation coefficient (TSC) lower than 20% was considered as iron deficiency (ID)." (PMID 34684033, 2021). "A thorough assessment of iron metabolism parameters, including iron serum levels, transferrin (with transferrin saturation), and ferritin allows differentiating iron deficiency from anemia related to chronic diseases or combined anemia, which commonly occur." (PMID 33924119, 2021). "The new insight about the functional role of transferrin in honey bee’s immune response to iron deficiency caused by microsporidia Nosema infection is a significant contribution to the existing body of literature concerning iron homeostasis in insects." (PMID 33600478, 2021). "Conversely, functional iron deficiency is defined as serum ferritin 100-299 μg/L, with transferrin saturation < 20%." (PMID 34568981, 2021). "Our anemic HTX patients had lower iron levels and transferrin saturation indicating possible mild iron deficiency although erythrocytes were normocytic and normochromic." (PMID 34078389, 2021). "To assess the impact of iron deficiency on Th17 CD4+ T-cells we used an in vitro iron deficiency model of Th17 polarisation in which iron is titrated into iron depleted media in the form of iron-saturated transferrin (Tf), known as holotransferrin (holoTf)." (PMID 34880854, 2021). "Most of the studies published so far on the role of transferrin as a mediator of antimicrobial immunity in the context of iron deficiency have focused on bacterial infections." (PMID 33600478, 2021). "In >Your< Iron Syrup group, several markers of iron deficiency, such as serum iron concentration, transferrin saturation and ferritin level were significantly improved in both female and male mice." (PMID 33922324, 2021). "Serum ferritin, serum iron, total iron-binding capacity (TIBC), and transferrin levels, the common biomarkers for iron deficiency, fluctuate with an acute and chronic infection or inflammation." (PMID 34031430, 2021). "Despite that, the lower iron concentrations found in diabetic women indicate a tendency towards iron deficiency anaemia, even because transferrin saturation is lower in the diabetic women group than in the other groups." (PMID 33591627, 2021). "Variants at DUOX2, F5, SLC11A2 and TMPRSS6 associate with iron deficiency anemia, while variants at TF, HFE, TFR2 and TMPRSS6 associate with iron overload." (PMID 33536631, 2021). "At entry, all 39 study participants from Europe met at least one criterion for iron deficiency (serum iron, ferritin, or transferrin saturation); 28 (74%) met the sTfR threshold >28.1 nmol/L." (PMID 33735594, 2021). "Among the parameters traditionally used to assess iron deficiency are the soluble iron in the blood, the iron in ferritin storage, transferrin, and transferrin saturation." (PMID 34575361, 2021). "Although iron levels are normal, increased transferrin saturation index (TSI) in both sexes indicates a tendency towards iron deficiency anaemia by inflammation." (PMID 33591627, 2021). "First, N. ceranae infection was found to cause honey bee iron deficiency and elevated expression of transferrin, an iron binding and transporting protein, implying that N. ceranae has evolved a mechanism to scavenge iron from the host." (PMID 33600478, 2021). "Measurement of ferritin level, the most specific marker of iron deficiency, was the most common laboratory test recommended by respondents (302 of 325 [92.9%]), followed by total iron-binding capacity and transferrin saturation (278 of 325 [85.5%])." (PMID 34596670, 2021). "Reciprocally, the connection of IRPs with the IREs of transferrin and receptors, which lie on the 3′-portion of the mRNAs, would restrain the process of mRNA degradation, resulting in an increase in transferrin in iron deficiency." (PMID 34660571, 2021).
iron deficiency (continued). "Diagnosis and investigation of iron deficiency requires many parameters which include serum ferritin, serum iron, total iron binding capacity, serum transferrin, and transferrin saturation." (PMID 34804607, 2021). "As serum ferritin can be high in CKD patients secondary to inflammation, serum ferritin is often used with transferrin saturation (Tsat) to assess iron status, diagnose iron deficiency, and predict response to iron supplementation." (PMID 34812298, 2021). "We, therefore, conclude that increased expression of transferrin is an indication of iron deficiency in disease-infected honey bees." (PMID 33600478, 2021). "Several markers of iron deficiency, such as serum iron, transferrin saturation, and hepatic ferritin level were significantly improved by administration of >Your< Iron Syrup and a positive control Fe-sulphate in both sexes." (PMID 33922324, 2021). "Both transferrin saturation and serum ferritin levels were found as informative markers in different underlying iron deficiencies in humans." (PMID 33922324, 2021). "All patients had idiopathic or heritable PAH and iron deficiency at entry as defined by a serum ferritin <37 μg/L or iron <10.3 μmol/L or transferrin saturations <16.4%." (PMID 33735594, 2021). "Mean hemoglobin, ferritin adjusted for C‐reactive protein (CRP), serum iron, transferrin saturation, prevalence of anemia, iron deficiency, and iron deficiency anemia as well as anthropometrics were compared between the groups at baseline, 3, and 6 months." (PMID 32724619, 2020). "Serum ferritin < 100 μg/L or transferrin saturation < 20% was recommended to detect the iron deficiency in patients with chronic heart failure, chronic kidney disease, and inflammatory bowel disease." (PMID 32985539, 2020). "In a mouse model of diet-induced subclinical iron deficiency, curcumin administration resulted in a dose-dependent reduction of hematocrit, hemoglobin, serum iron and transferrin saturation, exacerbating iron deficiency anemia." (PMID 32429125, 2020). "In H. pylori infected patients, a higher systemic level of transferrin has been observed in conjunction with iron deficiency." (PMID 33396581, 2020). "Low transferrin saturation, ferritin ≥ 100 μg/L, iron level < 12 μmol/L, functional iron deficiency, and anemia independently predicted all-cause death." (PMID 33292849, 2020). "The uptake of iron by apo-transferrin and monoferric transferrin species is of physiological importance for the hemopoietic tissues and also of pharmacological importance for the treatment of iron deficiency anemia." (PMID 32545424, 2020). "Consistently, Vitamin A serum levels are positively related to iron indices (serum iron, hemoglobin and transferrin saturation) in humans and its deficiency often co-occurs with iron deficiency anemia in some populations." (PMID 32429125, 2020). "One working definition of iron deficiency is ferritin <12 μg/L or transferrin saturation <16% or soluble transferrin receptor >28.1 nmol/L.15 25 By this definition, 10% of our participants were iron-deficient." (PMID 32565444, 2020). "Other laboratory indicators for iron deficiency mainly include serum iron (SI), transferrin (TRF), transferrin saturation (TS), and the total iron‐binding capacity (TIBC)." (PMID 32320096, 2020). "Laboratory data of the discussed patient showed significantly reduced levels of all iron status parameters (serum iron, transferrin saturation and ferritin) and confirmed the diagnosis of iron deficiency." (PMID 32468113, 2020). "The sTfR, MCH and transferrin indicated moderate accuracy in discriminating children with IBD with iron deficiency from iron-replete children with IBD." (PMID 32397525, 2020). "Laboratory investigations demonstrated iron deficiency anemia (hemoglobin 8.1 g/dL, serum iron 2 μmol/L, ferritin 14.4 μg/L, total iron-binding capacity 68 μmol/L, transferrin saturation 2.9%), and hypokalemia (potassium 2.7 mmol/L)." (PMID 33024574, 2020).
iron deficiency (continued). "Before surgery, 26 patients (male:female, 4:22) had iron deficiency (serum ferritin < 30 μg/L) and 10 (male:female, 1:9) had a transferrin saturation of < 20% and serum ferritin of < 100 μg/L." (PMID 32985539, 2020). "Bone marrow biopsy, serum ferritin levels, transferrin saturation, the mean corpuscular volume, and mean corpuscular hemoglobin concentration were used in the diagnosis of iron deficiency." (PMID 33053625, 2020). "The definition of iron deficiency in this trial and other cardiovascular trials differed significantly from the low ferritin definition used in previous studies, with transferrin saturation being added as a diagnostic parameter." (PMID 32215702, 2020). "Studies have shown that the prevalence of iron deficiency in adults with obesity is remarkable, and a decrease in serum iron and transferrin saturation levels is inversely associated with an increase in body mass index." (PMID 32564308, 2020). "Future studies should adopt the use of transferrin saturation (TSAT) in compliment with serum ferritin assay as a more sensitive marker of iron deficiency." (PMID 31971986, 2020). "The iron studies pointed conclusively to an iron deficiency with iron levels < 2 umol/L (reference range 9–30), and low iron stores with high transferrin levels of 3.9 g/L (reference range 2.0–3.6) and low transferrin saturations < 2% (reference range 15–45)." (PMID 32192459, 2020). "Only four patients showed low iron with low ferritin levels, with a low to normal range of transferrin, potentially indicating early-stage iron deficiency anemia." (PMID 33256142, 2020). "Iron studies confirmed iron deficiency anaemia (iron 6 μmol/L, transferrin 4.0 g/L, total iron binding capacity 100 μmol/L, transferrin saturation of 6%)." (PMID 31207533, 2019). "They reported that the frequency of anemia in the hemodialysis patients was 57.6%, iron deficiency anemia was observed in 31.1%, and 29.16% of the subjects had transferrin saturation of less than 20%." (PMID 30783118, 2019). "Materials and Methods: This was a prospective observational study that included patients diagnosed with heart failure and iron deficiency (defined by ferritin <100 μg/L, or 100–300 μg/L with transferrin saturation <20%)." (PMID 31269687, 2019). "Plasma ferritin levels (iron deficiency: <30 ng/mL) and transferrin saturation values (iron deficiency: <20%) remain the widespread biomarkers in defining iron deficiency in clinical practice." (PMID 31601941, 2019). "In absolute iron deficiency, reduction of serum iron would indicate a more readily available transferrin for iron binding (giving rise to increased TIBC)." (PMID 31640237, 2019). "The percent saturation of transferrin is strongly reduced (less than 10%) as in other forms of iron deficiency; however, at variance with iron deficiency, levels of serum ferritin are normal/increased." (PMID 31649559, 2019). "Consistent results were obtained for transferrin saturation (individuals with TS < 16% were typically defined as having iron deficiency)." (PMID 31270335, 2019). "The decrease of PON-1 activities has been associated with serum ferritin and transferrin in several diseases, such as Parkinson disease, inflammatory bowel disease, iron deficiency anemia, hereditary hemochromatosis with iron overload, and in beta-thalassemia." (PMID 31366068, 2019). "In CKD patients with iron deficiency, ferritin levels were significantly lower in the 2–6 year-old age group (44.86 ± 53.08 ng/mL, p < 0.001); however, the lowest age group with transferrin saturation was 0–2 years (21.68 ± 13.51%, p = 0.001)." (PMID 30700016, 2019). "Despite their ease of use, there are limitations to the sensitivity and specificity of transferrin saturation and serum ferritin in the diagnosis of iron deficiency." (PMID 30042411, 2018). "Ferritin is considered an indicator for determining iron deficiency, but serum ferritin levels had weak correlations with serum iron levels and transferrin saturation." (PMID 30275363, 2018).
iron deficiency (continued). "In clinical practice, iron deficiency is defined based on a combination of two commonly used markers, ferritin and transferrin saturation (TSAT)." (PMID 30208847, 2018). "Women were divided in two groups, one with IDA (serum ferritin < 12 μg/L) and one without (serum ferritin 12 to 200 μg/L); the former was further divided in latent, mild and moderate iron deficiency on the basis of transferrin saturation." (PMID 30429667, 2018). "Previous uncontrolled trials of iron supplementation in SCD have shown moderate responses in hemoglobin to iron supplementation in children with possible iron deficiency, defined as either low transferrin saturation, low MCV for age or low ferritin." (PMID 30056060, 2018). "In this case, the diagnosis of iron deficiency was established if all the following four criteria were present: low serum iron <45 μg/ dL, low transferrin saturation (TS) <16%, high TIBC ≥450 μg/dL, and low MCV for age." (PMID 29673144, 2018). "Plasma iron concentration is the resultant of iron transported to the plasma, free iron-binding sites on transferrin, and iron demand for erythropoiesis, which is increased in iron deficiency and in hemolytic anemias." (PMID 30201907, 2018). "A great number of patients (59%) were found with low transferrin saturation levels (<20%), which implies a high prevalence of iron deficiency." (PMID 29324643, 2018). "It is therefore recommended that serum iron and transferrin saturation be used to evaluate iron deficiency anemia." (PMID 30364423, 2018). "After the switch to FCM hemoglobin, hematocrit, serum ferritin, TSAT, and MCV increased, while transferrin levels decreased, reflecting erythropoiesis which is less restricted by iron deficiency." (PMID 30236065, 2018). "Our body tries to regulate transferrin levels to reach normalized hemoglobin in order to restore this anemia.These findings support the clinical importance of transferrin in iron-deficient anemia." (PMID 30246592, 2018). "Whereas, transferrin, an iron transport protein, and transferrin saturation is readily calculated to serve as a sensitive indicator of functional iron deficiency." (PMID 29762515, 2018). "Adding measures of iron-deficient erythropoiesis such as transferrin iron saturation improves sensitivity for detection of iron deficiency." (PMID 28898272, 2017). "Functional iron deficiency characterized by low serum transferrin saturation with normal or high serum ferritin is easily observed in CKD patients." (PMID 29077007, 2017). "Iron deficient erythropoiesis (ferritin < 12 μg/L and plasma iron < 500 μg/L) was observed in 5.4% and 16.9% had early functional iron deficiency (transferrin saturation < 15%)." (PMID 28898272, 2017). "Laboratory tests in iron deficiency anaemia usually depict a classical panel characterized by low serum levels of iron and ferritin, reduced transferrin saturation, and increased transferrin concentration." (PMID 28191453, 2017). "Serum iron, which indicates the amount of circulating iron that is bound to transferrin, is markedly reduced in iron deficiency anemia." (PMID 28046016, 2017). "Additional tests such as serum ferritin, serum iron and transferrin or total iron binding capacity(TIBC) were required for diagnosis of iron deficiency anemia." (PMID 28523045, 2017). "Iron deficiency (transferrin saturation less than 20%) was found in 645 (42.6%)/ 1513 patients; of whom 500 (33.0%) had iron deficiency." (PMID 28989585, 2017). "In HF patients, iron deficiency can be defined as ferritin <100 mg/L (absolute iron deficiency, related to depletion of iron stores), or 100–300 mg/L with transferrin saturation <20% (functional iron deficiency, related to systemic inflammation)." (PMID 27455314, 2016). "Mean ferritin in the ID group was 6.4 μg/l and transferrin saturation 8.4%, indicating profound absolute iron deficiency." (PMID 27140401, 2016).
iron deficiency (continued). "Plasma transferrin levels tend to increase in patients suffering from iron deficiency anemia and Mansour & Farid have shown an association between S. mansoni infection and anemia." (PMID 27138990, 2016). "On the basis of Hb cutoff value for anemia for different age group and transferrin saturation cutoff < 16 for iron deficiency, 35.2 % (n = 80) and 43.6 % (n = 99) children were anemic and iron deficient respectively." (PMID 26819633, 2016). "The characterisation of anaemia in critical care patients is currently challenging as the tests routinely used to screen for iron deficiency, such as ferritin and transferrin, are confounded by the presence of inflammation." (PMID 27681259, 2016). "Transferrin is involved in iron transport and distribution in all tissues, and elevated levels are associated with iron deficiency anemia." (PMID 26578919, 2015). "Among these genes, erythropoietin (EPO), PDGF, and transferrin are of particular interest in exploring the link between iron deficiency anemia and bone health." (PMID 25849944, 2015). "WHO experts recommend testing of hemoglobin, transferrin serum receptor and serum ferritin or fundamental iron studies to diagnose iron deficiency." (PMID 26445270, 2015). "The second phase (iron deficiency) is characterized by the reduction in serum ferritin and serum iron, and an increase in serum transferrin and its receptor (sTfR) in an attempt to enhance iron transport to tissues, but transferrin saturation falls." (PMID 25849944, 2015). "A disturbance in iron homeostasis is a hallmark of the anemia of CKD patients, which, usually, presents as a functional iron deficient anemia, with low serum iron and transferrin alongside with normal or even high ferritin." (PMID 25867633, 2015). "Some authors have proposed that significant losses of transferrin in heavy proteinuria resulted in iron-deficiency anemia." (PMID 26430892, 2015). "The combination of ferritin and transferrin saturation (TSAT) has been largely utilized as the routine parameters to assess iron deficiency." (PMID 26517509, 2015). "The diagnosis of iron deficiency anaemia was made only if all the three biochemical parameters like serum iron, serum ferritin, and percentage saturation of transferrin were below normal for the sex." (PMID 25400943, 2014). "Patients with absolute iron deficiency (transferrin saturation (TSAT) <20% and ferritin <40 ng/mL) had the lowest hepcidin levels (5.0 ng/mL [0.7–11.7]), and those with a normal iron profile (TSAT ≥20% and ferritin ≥40), the highest (34.5 ng/mL [23.7–51.6])." (PMID 24978810, 2014). "Percent transferrin saturation is the percent iron bound to transferrin (an iron carrier protein), and is also a measure of iron deficiency." (PMID 25375360, 2014). "While serum iron and transferrin (which binds iron and becomes low in the case of iron deficiency) are depressed in the presence of inflammation, ferritin (which decreases with iron deficiency) rises in the presence of inflammation." (PMID 25310252, 2014). "Any mutation in HFE causes increased transferrin which the intestines misinterpret as iron deficiency resulting in further increase in absorption of iron." (PMID 25431733, 2014). "Firstly, the transferrin saturation (cut off < 10%) has at best a sensitivity and specificity for iron deficiency similar to that of ferritin (cut off < 12 ng/ml) and hence does not provide an advantage." (PMID 25514884, 2014). "This is especially of importance to ferritin and transferrin saturation for which increasing number of women had levels indicative of iron deficiency from the first to the third trimester." (PMID 23758715, 2013). "The diagnosis of iron deficiency was established based on the following criteria: transferrin saturation (Ts) < 16% or serum ferritin (SF) < 25 ng/dL." (PMID 24288599, 2013). "Here mild iron deficiency was observed in Balb/c mice fed 3.5 ppm iron as reflected by a transferrin saturation of < 20% and lowered serum iron." (PMID 23800380, 2013).